SHKBP1 (SH3KBP1 binding protein 1)
Description:
Inhibits CBL-SH3KBP1 complex mediated down-regulation of EGFR signaling by sequestration of SH3KBP1. Binds to SH3KBP1 and prevents its interaction with CBL and inhibits translocation of SH3KBP1 to EGFR containing vesicles upon EGF stimulation.
Synonyms: SB1; PP203
Tractability: PROTAC: ubiquitination databases record sites on it; its protein half-life has been measured.
Gene: Protein-coding gene on chromosome 19 (40,576,844 to 40,591,399, forward strand). Ensembl gene ENSG00000160410.
Subcellular location: Lysosome
Subcellular location (Human Protein Atlas): Cell Junctions
Pathways (Reactome):
Signal Transduction: CDC42 GTPase cycle
Gene Ontology:
Molecular function: identical protein binding; protein binding
Biological process: positive regulation of epidermal growth factor receptor signaling pathway; protein homooligomerization
Cellular component: lysosome
Genetic constraint (gnomAD): Loss-of-function variants: 70 observed, 82.61 expected, observed/expected ratio (o/e) 0.85, 90% interval 0.7 to 1.03. The upper end of that interval is the gene's LOEUF score, 1.03, which puts it in group 4 of 6, group 1 being the genes least tolerant of losing a copy. Missense variants: 824 observed, 973.63 expected, observed/expected ratio (o/e) 0.85, 90% interval 0.8 to 0.9. Synonymous variants: 371 observed, 392.01 expected, observed/expected ratio (o/e) 0.95, 90% interval 0.87 to 1.03.
Homologues: Orthologues: chimpanzee SHKBP1 (100% identical), macaque SHKBP1 (95% identical), dog SHKBP1 (95% identical), pig SHKBP1 (95% identical), mouse Shkbp1 (93% identical), rat Shkbp1 (92% identical), guinea pig SHKBP1 (92% identical), tropical clawed frog shkbp1 (71% identical), zebrafish SHKBP1 (71% identical), Drosophila melanogaster CG9467 (50% identical), Caenorhabditis elegans T23B12.6 (42% identical). Paralogues in human: KCTD3 (64% identical).
Diseases named in the same sentence as SHKBP1 in open-access papers:
SHKBP1 is named in the same sentence as 22 diseases in open-access papers, as found by Europe PMC text mining. Sharing a sentence is not in itself a finding about the gene and the disease. The quoted sentences say what the papers report.
glioma (11 papers, 2018 to 2022). A benign or malignant brain and spinal cord tumor that arises from glial cells (astrocytes, oligodendrocytes, ependymal cells). "Another circRNA axises linked to glioma tumourigenesis and angiogenesis are the circ-SHKBP1/miR-544a/FOXP1 and circ-SHKBP1/miR-379/FOXP2 pathway." (PMID 31937318, 2020). "Another study indicated the involvement of circ-SHKBP1 in angiogenesis of glioma-exposed endothelial cells via miR-544a/FOXP1 and miR-379/FOXP2 pathways." (PMID 32549760, 2020). "FOXP1/FOXP2 are overexpressed since the upregulated molecule circ-SHKBP1 in glioma wound sequester their hunters-miR-544a/miR-379." (PMID 32518520, 2020). "circ-SHKBP1 regulated the angiogenesis of glioma-exposed endothelial cells through the miR-544a/FOXP1 and miR-379/FOXP2 Pathways." (PMID 31214170, 2019). "Circ-TTBK2 regulated the miR-217/HNF1b/Derlin-1 pathway to promote the progression of glioma; and circ-SHKBP1 regulated the angiogenesis of U87 glioma-exposed endothelial cells through miR-544a/FOXP1 and miR-379/FOXP2 pathways." (PMID 31179240, 2019). "The expression of circ-SHKBP1 is elevated in glioma-exposed endothelial cells (GECs), which functions as a ceRNA via the miR-544a/FOXP1 or miR-379/FOXP2 pathway." (PMID 30111313, 2018). "circ-SHKBP1 is highly expressed in high-grade gliomas, and knockdown of circ-SHKBP1 significantly inhibits cell proliferation and metastasis." (PMID 30064463, 2018). "Circ-SHKBP1 regulated the angiogenesis of GECs via the miR-544a/FOXP1 and miR-379/FOXP2 pathways, and these findings suggest that circ-SHKBP1 may be a useful target and method for combination therapy of gliomas." (PMID 35883576, 2022). "Circ-SHKBP1 regulates the angiogenesis of endothelial cells exposed to U87 glioma (GECs)." (PMID 35883576, 2022). "Therefore, circ-SHKBP1 promoted the movement and tube formation of glioma-exposed endothelial cells to boost angiogenesis via the circ-SHKBP1/miR-544a/FOXP1 and circ-SHKBP1/miR-379/FOXP2 axis." (PMID 32518520, 2020). "Hence, circ-SHKBP1 modulated glioma angiogenesis through targeting miR-544a/FOXP1/AGGF1 and miR-379/FOXP2/AGGF1 pathway." (PMID 32061256, 2020). "In addition, the expression of circ-SHKBP1 is elevated in glioma-exposed endothelial cells (GECs), and promotes the viability, migration and tube formation of GECs via the miR-544a/FOXP1 or miR-379/FOXP2 pathway via the AGGF1 itself or though the PI3K/AKT and ERK 1/2 pathways." (PMID 30111313, 2018). "Overall, circ-SHKBP1 modulated GEC angiogenesis via miR-379/FOXP2 and miR-544a/FOXP1 pathways, and these results could be used in a combination therapy for glioma." (PMID 34646821, 2021).
cervical carcinoma (6 papers, 2017 to 2025). A carcinoma arising from either the exocervical squamous epithelium or the endocervical glandular epithelium. "Recently, through a comprehensive genomic study of cervical cancer, SHKBP1 has been also identified as a mutated gene in the squamous subtype." (PMID 34001146, 2021). "Moreover, SHKBP1 is associated with various diseases such as cervical cancer, ovarian cancer, lung cancer, and osteoarthritis." (PMID 41445732, 2025). "One of the largest cervical cancer sequencing efforts—The Cancer Genome Atlas (TCGA) Project—reveals novel mutations in several genes, including SHKBP1, ERBB3, CASP8, HLA-A and TGFBR2, amplifications in immune targets PD-L1 and PD-L2, by sequencing 228 primary cervical cancer patients." (PMID 35205332, 2022). "One recent study of 228 cervical cancers using TCGA data identified SHKBP1, ERBB3, CASP8, HLA-A, and TGFBR2 as novel significantly mutated genes, and previously identified pathogenic genes including PIK3CA, EP300, ARID1A, and NFE2L2 were also confirmed." (PMID 28390392, 2017). "Finally, analysis of COSMIC db suggests SHKBP1 overexpression in pancreatic tumor (13.4%; FC = 2.05, p value < 0.001 extrapolated by GENT2 db) and cervical cancer (10.8%; FC = 2.14, p value < 0.05 by GENT2 analysis)." (PMID 34001146, 2021).
acute myeloid leukemia (2 papers, 2019 to 2021). Acute myeloid leukemia (AML) is a group of neoplasms arising from precursor cells committed to the myeloid cell-line differentiation. "Moreover, whole genome sequencing identified a missense mutation of SHKBP1 in acute myeloid leukemia (AML), which characterizes SHKBP1 as a putative proto-oncogene." (PMID 34001146, 2021).
lymph node metastasis (2 papers, 2013 to 2019). "Studies showed that compared with healthy individual’s serum, SHKBP1 protein expression in the serum of patients with lymph node metastasis and liver metastasis was significantly elevated, but studies on the regulating mechanisms SHKBP1 is few." (PMID 31138318, 2019). "Similarly for patients with lymph node metastasis we identified four proteins, namely IL1α, XIAP, STX2, and SHKBP1, whereas for patients with liver metastasis we identified IGF1, IL1α, IGFBP2, MAML3, and SHKBP1 as significant." (PMID 24282616, 2013).
gastric cancer (1 paper, 2021). A primary or metastatic malignant neoplasm involving the stomach. "For example, circ‐SHKBP1 and circ‐RanGAP1 in gastric cancer (GC) are reported to be up‐regulated and effectively delivered from GC‐derived EVs into the circulation." (PMID 33586248, 2021).
Sepsis (1 paper, 2025). Sepsis is defined as life-threatening organ dysfunction caused by a dysregulated host response to infection. "Our study provides a comprehensive analysis of CRGs expression in sepsis, establishes a diagnostic model, and identifies SHKBP1 as a biomarker for both diagnosis and prognosis prediction, offering new insights for sepsis management." (PMID 41445732, 2025). "Using this model, we identified five key genes for constructing the sepsis diagnostic model: SHKBP1, ICAM2, CTSD, SNX3, and SLC22A4." (PMID 41445732, 2025). "In conclusion, our study deeply explored the expression patterns of CRGs in sepsis, established a diagnostic model, and identified SHKBP1 as a biomarker that can be used for both diagnosis and prognosis prediction of sepsis." (PMID 41445732, 2025). "To validate the expression of SHKBP1 during sepsis, we performed RT-qPCR on lung tissues from septic mice." (PMID 41445732, 2025). "We established a diagnostic model based on five key genes(SHKBP1,ICAM2,CTSD,SNX3, and SLC22A4), and Kaplan-Meier survival analysis revealed that SHKBP1 was significantly correlated with both the diagnosis and prognosis of sepsis." (PMID 41445732, 2025). "In this study, we constructed a sepsis diagnostic model based on the mechanism of cuproptosis, revealing that SHKBP1 is an important gene not only related to the early diagnosis of sepsis but also predictive of patient prognosis." (PMID 41445732, 2025). "To clarify the potential biological roles of SHKBP1 in sepsis, we conducted further analysis on the GSE65282 dataset." (PMID 41445732, 2025). "Taken together, we have reason to believe that SHKBP1 is involved in the pathological mechanisms of sepsis and is related to its prognosis." (PMID 41445732, 2025). "Our findings indicated a strong association between SHKBP1 and immune processes, suggesting that SHKBP1 might play a critical role in the pathogenesis and progression of sepsis." (PMID 41445732, 2025). "In summary, SHKBP1 was identified as a gene that could both diagnose sepsis and predict patient prognosis." (PMID 41445732, 2025). "However, the relationship between SHKBP1 and sepsis remains unclear." (PMID 41445732, 2025).
tumor (11 papers, 2013 to 2025). "Specifically, SHKBP1 is related to immune regulation and has been shown to be associated with tumor occurrence and metastasis." (PMID 41445732, 2025). "The experiments conducted also resulted in the successful detection of circ-SHKBP1 in human blood plasma patients diagnosed with neoplasm of an uncertain nature of the brain and central nervous system." (PMID 34207029, 2021). "Furthermore, serum protein profiling identified SHKBP1 as a candidate in earlier detection of small intestine neuroendocrine tumor (WD-SI-NETs) tumor." (PMID 34001146, 2021). "The protein profiles of nine targets, namely IGFBP2, IGF1, SHKBP1, ETS1, IL1α, STX2, MAML3, EGR3 and XIAP were verified as significant contributors to tumor classification." (PMID 24282616, 2013). "The most important findings suggested that IGF1, IL1α, SHKBP1, and EGR3 were able to distinguish between controls and primary tumor-bearing patients." (PMID 24282616, 2013). "Therefore, both SHKBP1 and RRAD probably contributed to tumor development and drug resistance through RTK/RAS-related regulations." (PMID 34616428, 2021). "Similarly to its paralog SHKBP1, analyses performed on COSMIC database point out KCTD3 overexpression in other tumor types, such as breast cancer (14.2%; FC = 1.3, p value < 0.001 in the GENT2 db) and stomach (13%; FC = 1.83, p value < 0.001 by GENT2 analysis)." (PMID 34001146, 2021).
cancer (4 papers, 2019 to 2022). A tumor composed of atypical neoplastic, often pleomorphic cells that invade other tissues. "Circ_SHKBP1 levels are higher in cancer tissues and exosomes derived from patient serum and cancer cell lines." (PMID 35055115, 2022). "Circular SHKBP1 (circSHKBP) exerts momentous functions in the occurrence of many cancers including LSCC." (PMID 35502885, 2022).
cardiovascular disease (1 paper, 2011). "Moreover, SHKBP1 has not been specifically linked to cardiovascular disease prior to our study." (PMID 21756327, 2011). "An examination of the literature and annotated disease databases indicates that TRAF2, SHKBP1 and UBC have not been widely investigated in the context of cardiovascular disease, and that no quantitative links have been made to clinical response after MI." (PMID 21756327, 2011).
SHKBP1 also shares sentences with these, for which no sentence is quoted: infection (8 papers); bacterial infection (2); ovarian carcinoma (2); autoimmune disease (1); avian diseases (1); chronic lymphoid leukemia (1); diabetes (1); E. coli infection (1); gram-negative bacterial infections (1); lung carcinoma (1); osteoarthritis (1); osteomyelitis (1); osteosarcoma (1).